STAT3 (signal transducer and activator of transcription 3)
Diseases named in the same sentence as STAT3 in open-access papers (continued):
Sharing a sentence is not in itself a finding about the gene and the disease.
Peritoneal Fibrosis (continued). "In our previous work, we demonstrated that that IL‐6 trans‐signalling activates STAT3 in HPMCs and participates in the MMT process to promote peritoneal fibrosis." (PMID 38780509, 2024). "Ding and his team created peritoneal fibrosis in mice by injecting high glucose dialysate (HG-PDF) intraperitoneally, which led to the phosphorylation of STAT3 and an influx of macrophages into the peritoneal cavity." (PMID 39749340, 2024). "We demonstrated that HDAC8 promoted the EMT of HPMCs via EGFR/ERK1/2/STAT3/HIF-1α, induced M2 macrophage polarization via STAT6 and PI3K/Akt signaling pathways, and ultimately accelerated the process of peritoneal fibrosis." (PMID 36911746, 2023). "Inhibition of autophagy with 3-MA prevents peritoneal fibrosis by regulating TGF-β/Smad3, EGFR/ERK1/2, STAT3/NF-κB and β-Catenin axis both in vivo and in vitro systems." (PMID 34497522, 2021). "Our study indicated that the HG/STAT3/HIF-1α signaling pathway might involve in all those processes and the treatment using STAT3 inhibitor could partly attenuate the progression of peritoneal fibrosis, angiogenesis and inflammation." (PMID 34193173, 2021). "This suggests that reduced phosphorylation of STAT3 and ERK1/2 secondary to inhibition of TGF-β1 signaling by suramin may serve as a mechanism by which suramin attenuates peritoneal fibrosis." (PMID 31727005, 2019). "Finally, we lacked evidence of the relationship between peritoneal fibrosis and STAT3 phosphorylation in PD patients, which will be supplemented and improved in our further studies." (PMID 38780509, 2024). "However, the effect of STAT3 inhibitor on the progression of peritoneal fibrosis in vivo is still not clear." (PMID 34193173, 2021). "This study provided the first evidence that pharmacological inhibition of STAT3 prevented peritoneal fibrosis through the HG/STAT3/HIF-1α signaling pathway, indicating STAT3 inhibitor might be an effective therapeutic strategy for PF in PD patients undergoing long-term treatment." (PMID 34193173, 2021). "Thus, in addition to the TGF-β/Smad3 signaling pathway, Src may also regulate the EMT and peritoneal fibrosis through activation of the PI3K/Akt and STAT3 pathways." (PMID 29137389, 2017). "Moreover, inhibition therapy targeting EZH2 in both models alleviated peritoneal fibrosis and suppressed the activation of various pro-fibrotic signaling pathways, such as TGF-β1/Smad3, Notch1, EGFR, and Src, as well as phosphorylation events involving STAT3 and NF-κB." (PMID 39749340, 2024).
Thrombocytopenia (15 papers, 2016 to 2026). A reduction in the number of circulating thrombocytes. "In this study, we retrospectively analyzed a rare case of STAT3 GOF mutation with thrombocytopenia, immunoglobulin deficiency, and recurrent respiratory infections." (PMID 40703313, 2025). "Recurrent thrombocytopenia may activate the JAK2/STAT3 pathway, leading to megakaryocyte differentiation and platelet biogenesis." (PMID 38974233, 2024). "Whether other different TRAs can exert therapeutic effect on carboplatin-induced thrombocytopenia through mechanism other than reactivating JAK2/STAT3 pathway needs further investigation in the future." (PMID 35682967, 2022). "Furthermore, compared to human rIL-11 its macaque orthologue is 8-fold more effective STAT3 activator, which favors its use for treatment of thrombocytopenia as a potent substitute for human rIL-11." (PMID 27916836, 2016). "The increased with regard to human rIL-11 ability of macaque rIL-11 to STAT3 activation and its high homology to the human protein indicate potential usefulness of macaque rIL-11 for treatment of thrombocytopenia and similar pathologic conditions requiring stimulation of hemopoiesis." (PMID 27916836, 2016). "Furthermore, the higher potency of macaque IL-11 to STAT3 activation in the genetically modified HEK293 cells could be therapeutically significant in treatment of thrombocytopenia." (PMID 27916836, 2016). "Our findings establish CCR5 as a therapeutic target for thrombocytopenia and identify miltefosine as a CCR5 agonist that promotes MK differentiation and platelet production via MAPK and JAK2/STAT3 signaling." (PMID 40292315, 2025). "Prospective studies are needed to demonstrate any modifications of the JAK2/STAT3 pathway following thrombocytopenia and to determine whether the JAK2/STAT3 pathway may contribute to hyperprogression." (PMID 38974233, 2024). "Moreover, elevated JAK2 copy number and aberrant activation of the JAK2/STAT3 pathway, which are negative feedback pathways for thrombocytopenia, contribute to platelet biogenesis and immune escape." (PMID 38974233, 2024). "In addition to the intrinsically increased number of JAK2 copies, recurrent thrombocytopenia and TPO application might activate the JAK2/STAT3 signaling pathway as a feedback mechanism to stimulate thrombopoiesis." (PMID 38974233, 2024). "Without the reactivation of JAK2/STAT3 pathway, TPO is unlikely to be effective enough to treat carboplatin-induced thrombocytopenia." (PMID 35682967, 2022). "However, while effective in preclinical settings of a variety of different cancers including GBM, inhibition of STAT3 fails to provide a viable therapeutic option as STAT3 regulates many other necessary biological processes, and inhibition results in unintended side effects such as thrombocytopenia." (PMID 33496872, 2021).
cholestasis (14 papers, 2016 to 2025). Impairment of the bile flow caused by obstruction within the liver, or outside the liver in the bile duct system. "CONCLUSION: Cholestasis-induced STAT3- and JNK-pathways may predispose HBsAg-associated tumorigenesis." (PMID 28881751, 2017). "GW4064 treatment in the PNAC mouse increased hepatic FXR binding to the Stat3 promoter, further increased STAT3 phosphorylation and upregulated Socs1 and Socs3 mRNA, and prevented cholestasis." (PMID 36848082, 2023). "Previous reports support a role for STAT3 signaling in cholestasis." (PMID 36848082, 2023). "The protective effect of FXR agonists in cholestasis may be mediated in part through stimulating STAT3 signaling." (PMID 36848082, 2023). "This positive correlation between PDC-E2 and pY-STAT3, presented in cholangiocytes, the cells primary affected in PBC, may suggest the role of PDC-E2-modulated STAT3 phosphorylation during development of cholestasis." (PMID 34737337, 2021). "Thus, this study proposes a novel mechanism by which FXR agonists may protect and reverse cholestasis in PNAC through activation of STAT3 signaling." (PMID 36848082, 2023). "Together, considering that LIN28B/IL-6/STAT3 regulation seems to be an inflammatory loop-driven CCA initiation and able to explain the function of LIN28B in an early step of cholestasis -accelerated CCA in vivo." (PMID 34837926, 2021). "We have shown that activated STAT3 and the closely related STAT5 protein protect from cholestasis-induced liver injury by partly overlapping molecular mechanisms that include regulation of EGFR." (PMID 27568040, 2017). "Online data mining suggested that cholestasis might upregulate ACER3 via transcription factors SP1, EGR1, and STAT3, which were determined as potential regulators of ACER3 expression and known to be activated by cholestasis." (PMID 40025008, 2025). "The protective effects of fenofibrate and DCHT on ANIT-induced cholestasis and liver injury coincident with the inhibition of mRNA expression of inflammation-related genes (Il6, Il1b, and Tnfa), as well as the suppression of JNK/SAPK, NF-ĸB and STAT3 pathways." (PMID 35370715, 2022). "We found an increased expression of phosphor-STAT3 in BDL rats, but P-STAT3/STAT3 ratio remained unchanged in the three groups, which suggests that STAT3 may not directly respond to cholestasis-related liver injury as well as enhancing fibrosis." (PMID 30662889, 2018).
colorectal adenocarcinoma (14 papers, 2010 to 2025). The most common type of colorectal carcinoma. "In mice, STAT3 mutation has been linked to colorectal adenocarcinoma, increased systemic inflammation, and accelerated wound healing." (PMID 32552789, 2020). "Regardless, we could speculate that the beneficial effects associated with STAT3 blockade in the muscle of animals bearing highly inflammatory tumors (such the C26 colorectal adenocarcinomas) are likely to overcome the toxicities of the drug per se." (PMID 31018508, 2019). "PIWIL2 bound with piRNA-54265 to activate the STAT3 pathway and then promoted cell proliferation in colorectal adenocarcinoma." (PMID 41154843, 2025). "Phosphorylation of STAT3 is positively correlated with the tumor invasion of colorectal adenocarcinoma in human." (PMID 26871465, 2016). "Expression of p-STAT3 was immunohistochemically examined and was found 57.4% in 108 cases of colorectal adenocarcinoma tissue obtained at surgey." (PMID 26474284, 2015). "MMP-1 was observed to be up regulated in a STAT3-dependent manner in human colorectal adenocarcinoma and urinary bladder transitional cell carcinoma cells." (PMID 24743777, 2014). "A constitutively increased level of p-STAT3 was found in colorectal adenocarcinomas as opposed to STAT3 levels in the normal intestinal mucosa." (PMID 34443375, 2021). "Next, we therefore searched to determine whether the expression of STAT3 and DAT/SLC6A3 were correlated with the expression of other genes related to the STAT and NF-κB signals in colorectal adenocarcinoma patient-derived samples (594 cases)." (PMID 32102440, 2020).
dilated cardiomyopathy (14 papers, 2012 to 2025). Cardiomyopathy which is characterized by dilation and contractile dysfunction of the left and right ventricles. "Further, STAT3-deficient mice spontaneously develop a form of dilated cardiomyopathy similar to that which occurred in diabetic mice, indicating that reduced STAT3 activation may lead to myocardial remodeling." (PMID 23853776, 2013). "For example, cardiomyocyte-specific STAT3 deletion results in dilatative cardiomyopathy, characterized by increased apoptosis and interstitial fibrosis as well as reduced myocardial capillary density." (PMID 23841921, 2013). "The effects of the calreticulin-STAT3 signaling pathway on cardiac mitochondria and on the progress of dilated cardiomyopathy (DCM) are still unclear." (PMID 23818963, 2013). "We investigated the role of STAT3 in viral myocarditis and its possible role in the development to dilated cardiomyopathy." (PMID 22675647, 2012). "Furthermore, it has been also reported that Stat3 deficient mice developed dilated cardiomyopathy and patients with dilated cardiomyopathy had severely decreased myocardial Stat3 expression." (PMID 27496100, 2016). "The transcription factor (STAT3) is an important mediator of the inflammatory process, and in this original research the investigators examine the role of STAT3 in viral myocarditis and its possible role in the development to dilated cardiomyopathy." (PMID 23320244, 2012). "Thus, fibrosis, premature death, and dilated cardiomyopathy may be partially explained by the inflammatory response in STAT3 depleted cardiomyocytes." (PMID 37019881, 2023).
esophageal adenocarcinoma (14 papers, 2015 to 2025). A malignant tumor with glandular differentiation arising predominantly from Barrett mucosa in the lower third of the esophagus. "Previous reports demonstrated that inhibition of the STAT3/c-Myc was associated with induced apoptosis in esophageal adenocarcinoma cells." (PMID 35337104, 2022). "Excepts for the potential STAT3 gene amplification on chromosome 17q21, a region frequently amplified in esophageal adenocarcinomas, inflammation-associated STAT3 activation is also conceivable, at least in vivo." (PMID 25928665, 2015). "STAT3 might be associated with early events of Barrett’s esophagus." (PMID 28757556, 2017). "In esophageal adenocarcinoma, patients with higher STAT3 expression had a superior survival than those with a lower expression." (PMID 36977736, 2023). "For instance, CAF-secreted IL-6 induces STAT3 pathway activation, thus promoting epithelial-to-mesenchymal transition, growth, invasion, and chemoresistance of cancer cells in esophageal adenocarcinoma." (PMID 36635302, 2023). "Exposure of Barrett’s and esophageal adenocarcinoma cells to acidic bile salts activated EGFR-Stat3 signaling (EGFR-STAT3 protein complex) and induced the expression of Stat3 target genes (IL-6, IL-17A, BCL-xL, Survivin, and c-MYC)." (PMID 34884765, 2021). "This phenomenon was also observed in transformed Barrett’s and oesophageal adenocarcinoma cells when treated with honokiol (<40 μM) by targeting their STAT3 signalling pathway, thus resulting in a decrease of Ras activity and phosphorylated ERK1/2 expression." (PMID 31877856, 2019). "There is evidence that suggests the distinct signaling activity in the two main histological subtypes, with altered functional cellular responses following STAT3 inhibition in oesophageal adenocarcinoma (OAC) and SCC cells." (PMID 29890775, 2018). "Besides that, honokiol can induce necrosis and apoptosis in transformed Barrett’s and oesophageal adenocarcinoma cells through the inhibition of the STAT3 signalling pathway." (PMID 31877856, 2019).
idiopathic pulmonary fibrosis (14 papers, 2012 to 2025). Idiopathic pulmonary fibrosis (IPF) is a nonneoplastic pulmonary disease that is characterized by the formation of scar tissue within the lungs in the absence of any known cause. "In a study, paracrine signaling from fibroblasts derived from patients with idiopathic pulmonary fibrosis was shown to activate the IL-6/STAT3 and TGF-β/Smad3 pathways in healthy lung fibroblasts, contributing to fibrotic progression." (PMID 40806851, 2025). "In other diseases, ADAM17 participated in idiopathic pulmonary fibrosis (IPF) via miR-708-3p/ADAM17/STAT3 signaling pathway." (PMID 34182543, 2021). "Recent studies in patients with idiopathic pulmonary fibrosis (IPF) and PH have also shown increased expression of JAK2 and STAT3 in pulmonary arteries." (PMID 39125996, 2024).
intracerebral hemorrhage (14 papers, 2012 to 2026). A cerebrovascular disorder characterized by bleeding into one or both cerebral hemispheres including the basal ganglia and the cerebral cortex. "Phosphorylated STAT3 was observed in brain following intracerebral hemorrhage, a neurological condition associated with brain edema." (PMID 27918421, 2016). "Egr-1 increases RXRa acetylation by modulating p300, thereby exacerbating cerebral injury in a rat model of intracerebral hemorrhage and dysfunction in BMECs via the STAT3/NF-κB pathway." (PMID 38233877, 2024). "In brain, the protective effects of EPO are mediated via STAT3 activation, which promotes increased Bcl-2 and Bcl-xL in animal models of experimental intracerebral hemorrhage, and traumatic brain injury, and facilitates neuritogenesis." (PMID 24918289, 2014). "Other data have suggested that EPO treatment in intracerebral hemorrhage induces better functional recovery while reducing perihematomal inflammation and apoptosis via activations of eNOS, STAT3, and ERK." (PMID 22788969, 2012). "In intracerebral hemorrhage (ICH), eCIRP further amplifies inflammation via the interleukin-6 receptor (IL-6R)/signal transducer and activator of transcription 3 (STAT3) signaling pathway." (PMID 41750206, 2026). "In a study on intracerebral hemorrhage, it was found that the up-regulation of LncRNA SNHG3 can increase the permeability of BBB by activating TWEAK12/Fn14/STAT3 signal pathway." (PMID 35757529, 2022). "In experimental intracerebral hemorrhage, EPO reduction of inflammation and apoptosis was coupled with activation of eNOS, STAT3 and ERK." (PMID 24918289, 2014).
lymphopenia (14 papers, 2018 to 2025). Reduction in the number of lymphocytes. "Indeed, constitutive expression of a viral FLIP homolog in myeloid cells triggered a STAT3-linked, progressive, and fatal inflammatory syndrome in mice, characterized by elevated cytokine output, lymphopenia, lung injury, and multiple organ dysfunctions that mimicked human CRS." (PMID 34518653, 2022). "We also observed that lymphopenia was temporally associated with the upregulation of CCR2, LYN, PAK1, PTK2B, SRC, STAT3, which are involved in the chemokine signaling pathway." (PMID 30713538, 2018). "From an immunological perspective, patients with STAT3 GOF mutations are characterized by several hallmarks: More than half of the patients present with hypogammaglobulinemia and more than a quarter with NK cell lymphopenia, T cell lymphopenia, or B cell lymphopenia." (PMID 37140667, 2023).
mesothelioma (14 papers, 2015 to 2025). A usually malignant and aggressive neoplasm of the mesothelium which is often associated with exposure to asbestos. "We show that such a mechanism is relevant in vivo and underlies the action of butein, a dual STAT3-NFkB inhibitor capable of abating the chemoresistance of mesothelioma cells in vivo." (PMID 25868979, 2015). "Furthermore, the transcription factor STAT3, which controls the expression of genes regulating survival, proliferation and self-renewal, is frequently activated in many cancers, including mesothelioma, and is associated with oncogenic characteristics and poor survival." (PMID 36232554, 2022). "STAT3 activity was markedly decreased in mesothelioma specimens from SC144-treated mice, and in vitro treatment of mesothelioma cells with SC144 markedly reduced the expression of the STAT3 downstream effectors, cyclin D1 and survivin." (PMID 38784478, 2024). "The present results indicate that α-T3E acts as an effective anti-mesothelioma agent by disrupting the homeostasis of proteasomes through the simultaneous inactivation of STAT3 and NRF1." (PMID 35269802, 2022). "It is also reported that DDIT3 expression is suppressed by STAT3, leading to enhanced survival in mesothelioma." (PMID 29914181, 2018). "Taken together, rapamycin/crizotinib co-treatment affected aberrant cell signaling in an mTOR/ALK-positive mesothelioma graft by simultaneous blocking of mTORC1, AKT and STAT3." (PMID 29755689, 2018).
myelodysplastic syndrome (14 papers, 2014 to 2026). A clonal hematopoietic disorder characterized by dysplasia and ineffective hematopoiesis in one or more of the hematopoietic cell lines. "On the other hand, somatic heterozygous STAT3 gain-of-function mutations are also reported in literature in association with myelodysplastic syndrome." (PMID 34721429, 2021). "AZD9150 treatment caused knockdown of STAT3 expression in AML cell lines and human primary myelodysplastic syndrome (MDS)/AML stem cells, resulting in an increase in erythroid and myeloid differentiated colonies." (PMID 38424137, 2024). "Furthermore, in malignant hematopoietic cell disorders, STAT3 was considered a treatment target, and high STAT3 expression was observed in myelodysplastic syndromes." (PMID 33390934, 2020). "Another study reported that chidamide inhibited the viability of myelodysplastic syndrome and AML cells by suppressing JAK2/STAT3 signaling or inducing apoptosis via the accumulation of DNA damage and repair defects in AML stem and progenitor cells." (PMID 31850196, 2019).